CAT (catalase)
Diseases named in the same sentence as CAT in open-access papers (continued):
Sharing a sentence is not in itself a finding about the gene and the disease.
colitis (continued). "The levels of CAT, T-AOC, SOD and GPX in DSS-induced colitis mice decreased and the level of MDA increased." (PMID 37438752, 2023). "It is worth noting that the EUP-SeNP treatment group can significantly increase the levels of CAT(p < 0.0001) and GPX(p < 0.001) in colitis tissues, and also partly increase the levels of T-AOC and SOD." (PMID 37438752, 2023). "Colitis increased the levels of MDA and NO, and enhanced the inflammatory and apoptotic gene expressions, while reducing the SOD and CAT enzymes activity, and TAC levels in the colitis rats." (PMID 37647443, 2023). "The colitis model group in mice showed a significant (p < 0.01) increase in MDA (1.82-fold) levels and a decrease in the activities of SOD (54.7%), CAT (35.9%), and GSH-Px (32.6%) compared with their respective normal groups." (PMID 37375702, 2023). "Colitis significantly reduced SOD, CAT activity (p < .05), and TAC level (p < .001), in comparison to the control values." (PMID 37647443, 2023). "In this study, it was shown that the level of TAC and cell defense mechanisms, including antioxidant enzymes (SOD and CAT) was reduced, while oxidative stress indices such as MDA and NO were significantly increased, following induction of colitis." (PMID 37647443, 2023). "Caffeic acid has also exerted protective effects against colonic inflammation by increasing the levels of GSH-Px, CAT, and SOD in DSS-induced colitis." (PMID 36569313, 2022). "Compared to control colitis mice, treatment of colitis mice with MBZ suppressed the inhibitory effect of DSS on total thiol level as well as SOD and catalase activities." (PMID 35715495, 2022). "When curcumin microemulsion was added to the treatment of the colitis animals (COL/CUR group), tissue levels of SOD, catalase, and GSH-px were higher than in the COL/NS group (p < 0.001)." (PMID 35976279, 2022). "In a dextran sodium sulphate (DSS)-induced colitis mouse model, B. bifidum BGN4-SK treatment significantly enhanced levels of antioxidant enzymes SOD, glutathione peroxidase (GSH-Px) and CAT, compared to the DSS-only group." (PMID 35672695, 2022). "Prominently, administration of different levels of QT-NPs after colitis induction greatly increased (p < 0.05) the activities of GSH-Px, SOD and CAT enzymes in colonic tissues." (PMID 35884960, 2022). "Serum superoxide dismutase (SOD) and catalase (CAT) activities were significantly decreased, and serum malondialdehydes (MDA) levels were elevated in colitis rats induced by 5% DSS (p < 0.05)." (PMID 35269566, 2022). "Puerarin elevates the expression and protein content of Nrf2, as well as antioxidant enzymes such as CAT, GSH, SOD, HO-1, and NQO1, in mice with sodium glucan sulfate-induced colitis, indicating apparent oxidative protective effects." (PMID 36432411, 2022). "Treatment of colitis with catalase, the main enzyme responsible for H2O2 decomposition, attenuated the colitis." (PMID 33601276, 2021). "In the present study, increased oxidative stress was observed in AA-induced colitis rats, which was confirmed by increased MDA levels as well as decreased non-enzymatic antioxidant (GSH) levels and enzymatic antioxidant (CAT) activity in colon tissues." (PMID 33802553, 2021). "Increased concentrations of T-SOD and CAT, and decreased concentration of MDA in the plasma of mice with colitis were observed by EGCG-FMT compared with other three groups." (PMID 34493333, 2021). "The effect of ZS40 on oxidative stress in the serum of colitis was evaluated by monitoring antioxidant indicators and lipid peroxidation biomarkers, such as T-SOD, CAT, MPO, and MDA." (PMID 34867317, 2021). "DSS-suppressed concentrations of T-SOD and CAT, and DSS-increased level of MDA in the plasma in the mice with colitis compared with normal controls were largely attenuated by oral EGCG." (PMID 34493333, 2021). "Because the amount of catalase in the blood is low, and it was reported to be suppressed in DSS colitis and in patients with Crohn's disease." (PMID 33601276, 2021).
colitis (continued). "In the colitis model group, antioxidant enzyme activities in the colon were inhibited, and the enzymatic activities of GSH-Px, CAT and T-SOD, which can enhance antioxidant function, were significantly decreased compared to those in the Ctrl group." (PMID 34829556, 2021). "DSS significantly decreased the activities of endogenous antioxidant enzymes, including SOD, GSH-Px, catalase, and GSH, in the colon tissue of colitis mice." (PMID 33312339, 2020). "The compound was also effective to mitigate protein and lipid oxidative modifications and collaborated to normalize CAT and SOD activities in the colon of rats submitted to dextran sulfate-induced colitis." (PMID 33093936, 2020). "In this study, we found that, compared with no treatment, sinapic acid treatment significantly increased the levels of SOD, GSH-Px, catalase, and GHS in colitis mice." (PMID 33312339, 2020). "In this study, we demonstrated that the in vivo administration of the C. procera methanolic extract enhances SOD, CAT, and GPx activity in colonic tissue compared with the DSS group, contributing to the overall decrease in the severity of DSS-induced colitis." (PMID 32377161, 2020). "Moreover, we found that C. nitidissima Chi significantly elevated the activities of antioxidase, SOD, and CAT, and markedly decreased the level of MDA, suggesting that C. nitidissima Chi could prevent the colitis-associated colon carcinogenesis via improving the body's antioxidant ability." (PMID 28744216, 2017). "NAC exhibited an improved SOD effect (increase) versus the LA group, while LA increased CAT (versus NAC), GSH (versus mild colitis and NAC), and consequently GPx (versus control)." (PMID 27957238, 2016). "Mice with DSS-induced colitis presented with significantly increased activity of SOD (P = 0.012 compared to CTRL) in the colon and reduced CAT activity in MLN and spleen (P = 0.023 and P = 0.032, resp)." (PMID 27656047, 2016). "In the present study, the evaluation of oxidative and anti-oxidative stress markers indicated a markedly increased level of MDA and a reduced level of CAT and SOD in the colitis group, while treatment administration led to the restoration of tissue oxidative balance." (PMID 40896701, 2025). "DSS-induced colitis is characterized by elevated MPO activity, pro-inflammatory cytokines (TNF-α, IL-6, IL-1β), and lipid peroxidation, alongside depleted antioxidant defenses (SOD, CAT, GSH)." (PMID 41395463, 2025). "Thus, we assessed the main antioxidant enzymes (SOD1, SOD2, CAT, GPx) in a TNBS-induced colitis model in animals previously treated with BC." (PMID 40002416, 2025). "To evaluate the impact of SBP on oxidative stress in colitis, we measured the levels of total antioxidant capacity (T-AOC), catalase (CAT), and total superoxide dismutases (T-SOD) in both colon tissue and plasma, as well as the level of malondialdehyde (MDA) in the colon." (PMID 38732527, 2024). "Conversely, in a mouse model of colitis, Pingyin rose essential oil (PREO) was found to enhance the enzymatic activities of SOD and catalase (CAT), while reducing NO, malondialdehyde (MDA) and myeloperoxidase (MPO) production and restoring intestinal barrier integrity." (PMID 39360286, 2024). "The current data revealed that AA-induced colitis was accompanied by a notable increase in TBARS content and significantly reduced colon antioxidants as proven by the decreased GSH content and SOD, GST, GPx, and CAT activities." (PMID 37111290, 2023). "This suggests that, even in the presence of colitis, NAC was effective in recruiting CAT and efficient as a cysteine provider for later formation of GSH, given the abundant amount of acylase I in the renal tissue, thus replenishing the endogenous antioxidant reserve in the kidney." (PMID 37577725, 2023).
colitis (continued). "The catalase, SOD and GSH-px enzymes were detected in the colonic tissue at higher levels in the normal control group rats, in comparison to the groups of animals with colitis, submitted to the respective treatments (p < 0.001)." (PMID 35976279, 2022). "Colitis rats supplemented with 12 mg CAP/kg bw for 4 weeks decrease serum IL-6 levels and protein expression of TRPV1 and TRPA1 in the colon, and increase serum SOD and CAT activities and colonic IL-10 levels." (PMID 35269566, 2022). "Thus, the significant reduction of SOD and CAT by DSS treatment contributes to the tissue damage, similar to the colitis phenotype in human IBD patients." (PMID 28562346, 2017). "Data on the CAT mRNA level during DSS-induced colitis and upon HBO2 treatment were not available prior to this study." (PMID 27656047, 2016). "In the bet3+colitis group, oxidant parameters such as malondialdehyde and myeloperoxidase and antioxidant parameters such as SOD inhibition rate were found to be higher than in the control group, while antioxidant enzyme activity values such as catalase were found to be lower (p < 0.001)." (PMID 41515203, 2025). "As demonstrated in the present review, baicalin, diosmetin, fortunellin, luteolin, and wogonin could notably elevate the levels of the antioxidative enzymes SOD, GSH, GST, and CAT and suppress ROS and MDA activity induced by AA, DSS or TNBS treatment in the colitis tissue." (PMID 37324477, 2023). "However, in more severe GI cases in horses (e.g., colitis, obstructive colic), increased MDA and decreased catalase activity have been observed, so these markers could be useful for determining the severity of GI cases in elephants." (PMID 37174585, 2023). "Colitis rats induced by 5% DSS and supplemented with 100 mg LBP/kg bw for 4 weeks reduces serum lipid peroxidation substance MDA levels, colonic TNF-α, serum IL-6 levels, and the expression of pain signaling proteins TRPV1 and TRPA1 in the colon, and enhance serum antioxidative CAT activity." (PMID 35269566, 2022). "Moreover, the CAT activity was decreased by 33% in the vehicle-treated colitis group compared with the naive (noncolitis) group, and the treatment with HEBD (300 mg/kg) increased by 41% the activity of this enzyme compared with the vehicle group." (PMID 35295931, 2022). "However, DSS-induced suppression of the plasma concentrations of T-SOD and CAT in the mice with colitis compared with normal controls were not obviously impacted by rectal EGCG, though the level of MDA was also decreased." (PMID 34493333, 2021). "Similarly, although all treatments significantly improved superoxide dismutase (SOD), total thiol, and catalase (CAT) levels compared to colitis (P < 0.001), H2 with and without sulfasalazine was significantly more effective (P < 0.001)." (PMID 34345230, 2021). "Recent data indicate that intake of 1% GTPs diet aggravated colitis promoting colon carcinogenesis in mice treated with sodium dextran sulfate to induce colitis, while it decreased the activities of superoxide dismutase and catalase in nontreated mice." (PMID 32842591, 2020). "However, UCMSCs in DSS colitis did not influence the activity of catalase, which was similar to that for the DSS-treated mice." (PMID 25890182, 2015). "However, expression of “CAT” gene could not be demonstrated in other treatment groups since amplification could not be recorded in the colitis-induced mice as well as Lf1 fed-colitis-induced mice groups." (PMID 25061603, 2014). "It was observed that colitis, despite increased levels of SOD, which were probably due to increased levels of superoxide radical (O2·−) production, decreased CAT activity and the GSH/GSSG ratio and increased LP without raising H2O2 levels." (PMID 37577725, 2023). "Kidney was not affected by colitis; however, NAC despite increasing CAT, GSH, and GSH/GSSG ratio promoted lipid peroxidation (increased MDA) and pro-inflammatory action (decreased IL-10)." (PMID 37577725, 2023).
colitis (continued). "Following treatment with sinapic acid for 7 days, the levels of colonic antioxidant enzymes (SOD, GHS-Px, and catalase) and the nonenzymatic antioxidant GSH were significantly increased compared with those in DSS-treated colitis mice." (PMID 33312339, 2020).
depression (87 papers, 2013 to 2025). "For example, depression has been associated with low levels of natural antioxidants (enzymes such as catalase (CAT) and superoxide dismutase (SOD)) and vitamin E in the plasma." (PMID 37513187, 2023). "Specifically, in patients with pain-related TMD, the genotype AA of SOD2 polymorphism rs4880 was associated with higher hypervigilance scores, while the genotype CC of CAT SNP rs1001179 was associated with higher depression scores." (PMID 37371925, 2023). "Previous studies confirmed that c.-89 A > T—CAT (rs7943316) polymorphism was associated with the development of various diseases, including depression, infertility, keratoconus, thyroid, and hepatocellular carcinoma." (PMID 35732787, 2022). "The reduction of SOD activity associated with increased XO activity and unchanged CAT activity well explain the increased ROS generation detected in patients with depression." (PMID 33066277, 2020). "It was reported that there is a relationship between depression and polymorphisms in genes involved in oxidative pathways including CAT." (PMID 33126414, 2020). "A significant association between depression and polymorphisms in genes involved in oxidative and nitrative pathways, like manganese superoxide dismutase, catalase, and myeloperoxidase, is also known." (PMID 25838867, 2015). "SNPs in genes for IL-1, IL-6, tumor necrosis factor alpha (TNFα), cyclooxygenase 2 (COX2), superoxide dismutase (SOD), and catalase is associated with depression." (PMID 26078821, 2015). "Despite the abundance of studies highlighting the importance of oxidative stress biomarkers—including catalase (CAT), glutathione reductase (GR), and glutathione S-transferase (GST)—in the etiology of bipolar disorders, only a few articles address potential associations between CAT and depression." (PMID 40507778, 2025). "We showed in previous studies that exposure to these fields disturbs the antioxidant system balance, and leads to increased levels of malondialdehyde, catalase, and superoxide dismutase, which is also associated with poor sleep quality, stress, anxiety, and depression." (PMID 32710586, 2020). "The depression control group decreased CAT activity, which demonstrates an adaptive reaction to oxidative stress." (PMID 40574754, 2025). "The depression control group showed a lower level of CAT in the brain tissue when it was compared with group-1 (p < 0.0001)." (PMID 40574754, 2025). "In the rat model of depression, an insignificant reduction in catalase activity was shown in the hippocampus (− 40.01) compared to the control group." (PMID 37713054, 2024). "It was found that AGO can modulate oxidative stress in depression model mice by regulating CAT, thus highlighting new ideas for treating depression." (PMID 38335199, 2024). "Our data corroborate with previous studies conducted on psychiatric illness, including major depressive disorder and schizophrenia, showing high activity of CAT in individuals with major depressive disorder and schizophrenia." (PMID 38646205, 2024). "They revealed the excess of peroxisomes and intracellular H2O2 in the mouse brain, leading to CAT inactivation, dysfunction of the 5-HT system, and, ultimately, depression-related behaviors in mice." (PMID 38335199, 2024). "Some studies that have examined catalase activity in depressed patients have found increased levels of catalase activity during acute episodes of depression compared to healthy volunteers." (PMID 36901407, 2023). "We noted the correlation of depression severity with oxidative stress (CAT, GSH and SOD in serum, S-Nitrosothiols in urine)." (PMID 38002663, 2023). "According to Tsai and Huang, catalase activity is increased in patients in the acute phase of depression." (PMID 36901407, 2023). "Catalase is primarily a peroxisomal enzyme that catalyzes the enzymatic decomposition of H2O2, and in rats it is associated with depression-like behavior associated with Alzheimer’s disease improvement." (PMID 34073632, 2021).
depression (continued). "The A/T-G/G genotype of c.−89A > T(rs7943316) in CAT and c.−227G > C(rs10459953) in NOS2 was associated with a risk of depression (p = 0.001)." (PMID 32111088, 2020). "SOD, GSH-Px, CAT, and MDA levels were measured by enzyme-linked immunosorbent assay, and the 17-item Hamilton Depression Rating Scale and Young Mania Rating Scale were administered at baseline and the end of the 6th week." (PMID 31967315, 2020). "T/T-C/T genotypes of SNVs c.−89A > T(rs7943316) in CAT and c.1823C > T(rs2297518) in NOS2 increased the risk of depression (p = 0.002), while the T/T-T/T genotype reduced the risk (p = 0.036)." (PMID 32111088, 2020). "Oxidative stress was also reported to be implicated in several mental disorders including depression and anxiety, therefore we checked SOD and CAT activities in the PFC of Ghsr+/+ mice and Ghsr-/- mice, both at baseline state and after CSDS." (PMID 31057357, 2019). "By ELISA assay, we found that serum levels of H2O2 and 8-OHdG dramatically increased, and serum levels of CAT significantly decreased in GC patients with depression." (PMID 31396300, 2019). "Elevated activity of catalase was observed in patients in acute phase of depression and also in patients with bipolar disorder on lithium medication." (PMID 26078821, 2015). "Moreover, inhibiting ROS and malondialdehyde (MDA) and increasing antioxidant enzymes like superoxide dismutase and catalase (CAT) can alleviate depression symptoms." (PMID 39539631, 2024). "This study investigated the potential correlation of markers of oxidative stress (glutathione [GSH], catalase) with the number of demyelinating lesions and the degree of disability, cognitive deficit, and depression in patients with relapsing-remitting multiple sclerosis (RRMS)." (PMID 38623459, 2024). "Expressions of SOD1, CAT, IGF2 and IGF2R also decreased in the postmortem brain regions of individuals with AD and depression compared those of AD, suggesting that the stress-related disorder of depression is indeed a risk factor for AD and exaggerates OS." (PMID 38338968, 2024). "CAT and the CAT/TBARS ratio were negatively associated with the intensity of depression symptoms, suggesting that the training model of master sprinters may be more effective in increasing CAT and reducing depressive symptoms." (PMID 36901407, 2023). "However, findings on catalase and its relationship with the intensity of depression symptoms (DEPs) are still inconsistent." (PMID 36901407, 2023). "Expressions of CAT and SOD1 are also decreased in postmortem brain regions of individuals with AD and depression compared to those with AD alone, suggesting that the stress-related disorder of depression is indeed a risk factor for AD." (PMID 36453495, 2023). "The increase in catalase activity may reflect a compensatory mechanism since, during depressive disorders, there is an increase in oxidative and nitrosative stress (O&NS) pathways." (PMID 36901407, 2023). "Similarly, PJ presented a protective effect against the anxiety and depression induced by aluminum trichloride exposure through the enhancement of catalase, SOD, GST, and GSH." (PMID 35392110, 2022). "Specifically, nickel increases the hippocampal level of thiobarbituric acid reactive substances (TBARS) (markers of LPO), and decrease SOD and CAT activities which may culminate in increased anxiety-like and depression-like behaviour in rats." (PMID 35989698, 2022). "Finally, PCA revealed a positive correlation among LOX and BDNF and parameters determined in the anxiety tests, as between catalase activity and immobility time in the depression test." (PMID 36613269, 2022). "Based on these data, we could hypothesize that escitalopram targets depression associated oxidative stress through GSH/GSSG redox cycle, therefore this could lead to normalisation of catalase in response to the reduced oxidative stress." (PMID 34299103, 2021).